BCL6 (BCL6 transcription repressor)
Diseases named in the same sentence as BCL6 in open-access papers (continued):
Sharing a sentence is not in itself a finding about the gene and the disease.
tumor (continued). "In this study, we focused on the mechanism that BCL6 inhibits the tumor infiltrating CD4+T cells through ESM1, however, there are other mechanisms through which BCL6 promotes HCC progression." (PMID 38956432, 2024). "To find out the downstream potential target proteins which account for Bcl6-mediated tumor immune evasion, we applied bulk RNA sequencing to elucidate the gene transcription after Bcl6 knockout." (PMID 38956432, 2024). "We next assessed the functional impact of Tfh cells on tumor-specific CD8+ T cell response to anti-PD-1 mAb by targeting the BCL6 transcription factor." (PMID 38417020, 2024). "There is a growing recognition that in certain cancer types BCL6 instead functions as a tumor suppressor." (PMID 39456751, 2024). "IHC also showed that the staining intensity of FZD7 in the tumor tissue of BCL6-overexpressing nude mice was significantly weaker than that in the control group." (PMID 37060074, 2023). "The results showed that the staining intensity of BCL6 in the tumor tissue of the BCL6-overexpressing group was significantly stronger than that in the control group." (PMID 37060074, 2023). "The immunohistochemical score showed that the level of the BCL6 protein in GC tissues was significantly lower than that in the corresponding adjacent non-tumor tissues (N = 137, P < 0.001)." (PMID 37060074, 2023). "Simultaneously, the weight of the harvested tumor mass showed that BCL6 inhibited the proliferation of SGC-7901 and AGS cells in nude mice." (PMID 37060074, 2023). "MiR-155 is another miR known to be a tumour-promoting factor in many cancers by regulating the BCL6/cyclin D2 axis." (PMID 37242569, 2023). "The results showed that compared with the control group, the tumor metastases in the abdominal cavity of nude mice in the BCL6 overexpression group were substantially reduced, and the weight of the corresponding metastases was also significantly reduced." (PMID 37060074, 2023). "Subsequently, we constructed an intraperitoneal dissemination tumor model to explore the effect of BCL6 on the metastasis of GC cells in nude mice." (PMID 37060074, 2023). "Firstly, BCL6 was identified as an important biomarker that attenuated the proliferation and metastasis of GC through tumor microarrays and confirmed in GC cell lines." (PMID 37060074, 2023). "We analyzed the mRNA expression levels of BCL6 in 36 pairs of GC tissues and adjacent non-tumor tissues using qPCR and found that the mRNA level of BCL6 in 30 cancer tissues was lower than that in the matched para-carcinoma tissues (N = 36, P < 0.001)." (PMID 37060074, 2023). "B-cell lymphoma 6 (BCL6) is a transcription repressor that plays a tumor suppressor or promoting role in various tumors." (PMID 37060074, 2023). "They found that the overexpression of STAT3 in these samples was associated with an increase in the expression of Bcl6, a protein that plays a crucial role in EMT, tumor progression, decreased survival, and the viability of BCSCs." (PMID 37958993, 2023). "The data thus collectively indicated that TLR4-mediated Bcl6 induction was essential for macrophages differentiation underpinning tumor progression." (PMID 36542153, 2022). "Collectively, our data indicated that Bcl6 played a central role in governing SMMs commitment and hence tumor progression, making it a potential target for cancer immunotherapy by interfering trained immunity." (PMID 36542153, 2022). "Given that BCL6 is dynamically regulated in a tumor context-dependent manner, we thus extensively characterized the biological role of PTEN in BCL6-mediated drug tolerance." (PMID 35503721, 2022). "The findings indicated that descendants of Bcl6+ macrophages stably retained the phenotypic and functional properties formed in tumor niches." (PMID 36542153, 2022).
tumor (continued). "SMC3 haploinsufficiency accelerates lymphomagenesis in mice with constitutive BCL6 expression and is considered a putative tumor suppressor for germinal center B cells." (PMID 36499305, 2022). "The results thus underscored the importance of mTOR-mediated protein synthesis pathway in the induction of Bcl6 in tumor-conditioned macrophages." (PMID 36542153, 2022). "Our findings establish a rationale for the concurrent targeting of BCL6 to conquer tumor tolerance to genotoxic stress, as evidenced by the striking synergy of genotoxic therapy and BCL6-targeted therapy in vitro and in vivo." (PMID 35503721, 2022). "Our results demonstrated that tumor patients with higher BCL6 expression had a shorter 5-year survival rate than BCL6-low expression patients." (PMID 36377663, 2022). "Here, we report that the proto-oncogene BCL6 is a central component of the resistance pathway in tumor response to genotoxic agents." (PMID 35503721, 2022). "IRGD-Exo-BCL6 siRNA treatment remarkably reduced the expression of BCL6 and increased the expression of active caspase 3 in tumor tissues compared with the control or iRGD-Exo-siRNA NC group." (PMID 35982974, 2022). "Together, our data indicated that Bcl6+ TAMs adopted mitochondria-dominant metabolism to support their metabolic adaptiveness in nutrient-stressed tumor niches." (PMID 36542153, 2022). "BCL6 is involved in regulating the immune response of tumor-infiltrating regulatory T cells during the occurrence and development of various tumors." (PMID 35237300, 2022). "Taken together, our data indicated that tumor-elicited Bcl6+ macrophages adopted a hybrid status of stem and memory cells to maintain phenotypic and functional features initially impinged by tumors." (PMID 36542153, 2022). "As long-living memory macrophages is heavily dependent on metabolic fitness particularly in nutrient-stressed tumor milieu, we then analyzed the metabolic characteristics of Bcl6+ SMMs." (PMID 36542153, 2022). "Here, we show that BCL6 upregulation is a prominent mechanism to protect tumor cells from genotoxic killing." (PMID 35503721, 2022). "Somewhatdisappointingly, especially given that we had observed sustained depletionof BCL6 and potent antiproliferative effects in vitro, we only observeda modest decrease in tumor growth compared to the vehicle controlgroup." (PMID 35653645, 2022). "Together, our data consistently demonstrated the PI3K/AKT/mTOR pathway played a pivotal role in translating tumor-derived signals into Bcl6-mediated SMMs differentiation program." (PMID 36542153, 2022). "Second, the disadvantage of this study is that only one OCI-Ly8 cells was used in in vivo study, more DLBCL cells, such as OCI-Ly10 and SUDHL-10, are needed to further confirm the capacity of iRGD-Exo-BCL6 siRNA1 to suppress tumor growth in vivo." (PMID 35982974, 2022). "Significantly, exosomes mediated BCL6 siRNA delivery inhibited tumor growth in DLBCL with a low toxicity profile." (PMID 35982974, 2022). "Collectively, these data support the notion that BCL6 confers drug resistance and induces a targetable vulnerability in tumor cells." (PMID 35503721, 2022). "A PK/PD study showed that 50 mg/kg CCT373566 dosedorally depleted BCL6 for 12 h and beyond in tumor xenografts." (PMID 35653645, 2022). "Supportively, our data demonstrated that Tet2 was remarkably induced upon Bcl6 expression and reduced by Bcl6 deletion in tumor-conditioned macrophages." (PMID 36542153, 2022). "For this, Bcl6+ macrophages were isolated from tumor-bearing mice and cultured in vitro in tumor-free medium." (PMID 36542153, 2022). "Together, the results identified tumor-derived redHMGB1 as a priming signal to drive TLR4/mTOR/Bcl6-mediated trained immunity in TAMs." (PMID 36542153, 2022).
tumor (continued). "Significantly, iRGD-Exo electroporated with BCL6 siRNA inhibited tumor growth in vitro and in vivo; however, the equivalent dose of BCL6 siRNA delivery by blank-Exo had limited effect on inhibition of tumor growth." (PMID 35982974, 2022). "The combination of etoposide and BCL6 knockdown significantly impeded PANC28 tumor growth compared to etoposide treatment alone group." (PMID 35503721, 2022). "To further confirm the sensitizing action of BCL6 blockade to etoposide, we additionally set up a tumor xenograft mouse model using PANC28 cells that are more resistant of etoposide treatment than HCT116 cells." (PMID 35503721, 2022). "Given the center importance of Bcl6 in governing SMMs development, there arises the question how Bcl6 is induced and sustains during tumor development." (PMID 36542153, 2022). "In mouse models of melanoma and colon cancer, anti-PD-1 treatment induced the expansion of tumor Tregs with a follicular phenotype (Follicular regulatory T cells or Tfr, Foxp3+ Bcl6+), and Tfr depletion by pretreatment with anti-CTLA4 improved tumor control." (PMID 35874810, 2022). "In this study, we aimed to investigate the feasibility of delivering the BCL6 siRNA to tumor tissues in vivo using engineered exosomes." (PMID 35982974, 2022). "We thus concluded that Bcl6 was required and sufficient for the development of SMMs instructed by tumor-derived signals." (PMID 36542153, 2022). "We got the BCL6 expression in Ibrutinib pretreated tumor biopsy samples of ABC-DLBCL patients from GSE93984 dataset." (PMID 33629212, 2021). "Together, these data confirmed the screen result in identifying BCL6 as a potential paclitaxel resistance mediator, which upon knockdown or inhibition results in a further cancer cell/tumor growth disadvantage in the context of paclitaxel treatment." (PMID 33932086, 2021). "The expression of Bcl-2 and Bcl-6 in the transplant group was notably downregulated compared to control tumor." (PMID 33505491, 2021). "In PDX models, HDAC3 inhibition with BRD3308 reduced tumor growth, and induced upregulation of BCL6 target genes and MHC-II expression in the setting of both CREBBP-mutant and CREBBP-WT diseases." (PMID 35071240, 2021). "RT-qPCR examination of these tumor areas revealed a positive correlation between tumor burden and several immune genes found in ilea from pCC patients, such as Cd4, Bcl6, and Gata3." (PMID 33262469, 2021). "Of note, how BCL6 maintains the lineage stability and functional fitness of Treg cells specifically in tumor microenvironment remains unsolved." (PMID 34349770, 2021). "Inhibition of IRF4 enhances the expression of BCL6, thereby stabilizing the level of Tregs and suppressing the anti-tumor immune response." (PMID 33468159, 2021). "Hi-C contact maps revealed little difference globally between Smc3/Bcl6 vs Bcl6 tumor interactivity profiles." (PMID 34621263, 2021). "H2A.Z was shown to function via the tumor dysregulation signaling pathway, with BCL6 as its interacting protein." (PMID 34120148, 2021). "Because of the low numbers of Th1 and Tfh positive cells in tumor tissue, these immunostainings were validated by comparing two different mAb clones for each transcription factor (T-bet and BCL6), and similar results were obtained." (PMID 34868011, 2021). "Conversely, another study reported that miR-144 act as tumor suppressor by suppressing the BCL6 function in DLBCL xenografted mice." (PMID 34679437, 2021). "Six factors, including patient age, ocular involvement, tumor pattern, tumor size, BCL6 immunoreactivity, and Ki67 proliferative index, which tended to be associated with PFS, were included in the multivariate analysis." (PMID 34898570, 2021). "It has been demonstrated recently that BCL6 deletion in Treg cells significantly inhibited tumor progression." (PMID 34539626, 2021). "The initial tumor stasis in BCL6 knock-out tumors was followed by a slow but continuous tumor growth beginning around day 13 of the treatment." (PMID 32180900, 2020).
tumor (continued). "Our findings argue for the therapeutic potential of approaches focused on maximizing the impact on CD4+ Th-ctx activity through manipulation of the Blimp-1/Bcl6 axis in tumor-reactive CD4+ T cells." (PMID 31924474, 2020). "For comparison with BCL6 and in vitro data, gene expression analysis of BM-derived tumor cell populations was subsequently performed for BACH2." (PMID 32131762, 2020). "This subpopulation of BCL6 expressing cells increases over time, both in vitro and in vivo and contribute to a continuous tumor growth." (PMID 32180900, 2020). "To determine how CD62L- effector-type and CD62L+Bcl6+ memory-like T cells are generated, we analyzed activation and differentiation of antigen-primed OT-1 T cells in tumor-draining lymph nodes." (PMID 32845913, 2020). "These CD62L+ T cells were Bcl6+ and generated directly from CD62LintCD44high Bcl6+ T cells in tumor-draining lymph nodes." (PMID 32845913, 2020). "It is possible that tumor-infiltrating Bcl6+CD62L+ cells re-expressed Bcl6 while the expression of Bcl6 in CD62L- effector cells remained repressed by continuous stimulation." (PMID 32845913, 2020). "Altogether, we found that Bcl6 is a negative regulator of the suppressive function of Treg cells during anti-tumor responses." (PMID 32477338, 2020). "Collectively, these results indicate that Bcl6 actively participates in regulating Treg cell immune responses during tumorigenesis and can be exploited as a therapeutic target of anti-tumor immunity." (PMID 32477338, 2020). "This eventual expansion of the tumor escaper cells limits the time window in which the effects of BCL6 knock-out can be observed." (PMID 32180900, 2020). "Using flow cytometric analysis, we confirmed that tumor infiltrating Treg cells expressed higher level of Bcl6 than Treg cells derived from tumor dLNs and spleens in mice challenged with MC-38 cells subcutaneously (in situ model)." (PMID 32477338, 2020). "Immunohistochemical staining and qRT-PCR assays indicated that BCL6 was up-regulated in human CRC tissues compared with its adjacent non-tumor tissues." (PMID 32206063, 2020). "To better understand the role of Bcl6 in Treg cells during tumorigenesis, we examined tumor infiltrated effector T cell response after challenging Bcl6fl/flFoxp3Cre and WT mice with MC-38 cells subcutaneously." (PMID 32477338, 2020). "To this end, we transplanted LLC-OVA tumor cells into Bcl6-deficient OT-1 or wild-type OT-1 (CD45.2) mice, and then 7 days later sorted tumor-infiltrating CD62L+ OT-1 T cells." (PMID 32845913, 2020). "Although Bcl6-floxed OT-1 mice had fewer tumor infiltrating cells, CD62L+ cells were found in both mice with similar frequencies." (PMID 32845913, 2020). "Bcl6 deletion significantly down regulates the expression of Foxp3 in tumor infiltrating Treg cells, which critically specifies the Treg lineage and maintains its functional program." (PMID 32477338, 2020). "These cells gave rise to tumor-infiltrating CD62L-CD44high Bcl6- effector T cells and CD62L+CD44highBcl6+ memory-like T cells." (PMID 32845913, 2020). "Since Bcl6 was an essential factor for CD62L+ T cell expansion, it was suggested that CD62L+Bcl6+ T cells within the tumor played a relevant role to control tumor growth." (PMID 32845913, 2020). "Using real-time PCR, we observed an upregulation of Bcl6 transcripts in tumor infiltrating Treg cells when compared with dLNs derived Treg cells (TdLN Treg) and CD44–CD4+ T cells (naive CD4)." (PMID 32477338, 2020). "The biopsy revealed a diffuse proliferation made up of two types of tumor cells: centroblasts (Bcl-6-positive) and immature cells (terminal deoxynucleotidyl transferase-positive)." (PMID 32713346, 2020). "The enhanced expression of Bcl6 in tumor infiltrating Treg cells indicates an important but unsolved role of Bcl6 within TME." (PMID 32477338, 2020).
tumor (continued). "And tumor infiltrating Bcl6–/– Treg cells exhibited markedly decreased expression of Foxp3, while upregulating the expression of TFs and cytokines related to other lineages, including Tbet, RORγt, GATA3, IL4, and IL17, suggesting a weakened lineage stability." (PMID 32477338, 2020). "Tumor growth inhibition in mouse DLBCL xenograft models has been reported for several BCL6 inhibitors." (PMID 32180900, 2020). "An anti-proliferative response was observed 4–7 days after deletion of BCL6 in vitro whereas tumor stasis occurred in in vivo xenograft studies." (PMID 32180900, 2020). "Consistently, the in vivo xenograft models confirmed that knockdown of BCL6 partially abolished the accelerated tumor growth and the increased tumor size/weight induced by overexpression of LINC00152 (P < 0.05)." (PMID 33282727, 2020). "But how Bcl6 regulate Foxp3 expression and function of tumor infiltrating Treg cells remains unsolved in our study." (PMID 32477338, 2020). "In mice that received Bcl6+/+OT-1 T cells, tumor growth was well controlled, whereas larger tumors were detected in those received Bcl6-/-OT-1 T cells." (PMID 32845913, 2020). "In sum, 22 analyzed tumor draining LNs displayed 853 GCs, which were analyzed for area, roundness, and cellular composition of Bcl6+ PD1+ Tfh." (PMID 32824917, 2020). "At the time of tumor stasis (up to 8 days after start of DOX treatment) the xenografts contain 15% tumor cells which still express BCL6." (PMID 32180900, 2020). "Since the poor bioavailability of BI-3802 does not permit its use in animals, we wanted to apply the inducible knock-out system to investigate the effects of BCL6 depletion on tumor growth in vivo." (PMID 32180900, 2020). "U87-MG had cytoplasmic BCL6 in all cells and the primary tumor-derived line NZG-0906 had strong nuclear expression in the majority of cells." (PMID 32320427, 2020). "Meanwhile, we found that the absence of follicular regulatory T (Tfr) cells, which is a result of Bcl6 deletion in Foxp3+ cells, was dispensable for tumor control." (PMID 32477338, 2020). "Bcl6 expression in these T cells was critical because Bcl6-/-CD62L+CD44highCD8T cells within the tumor were defective in expansion after secondary transfer." (PMID 32845913, 2020). "According to our studies it is reasonable to predict that treatment of DLBCL with BCL6 degraders results in significant tumor growth inhibition and at least tumor stasis." (PMID 32180900, 2020). "Conditional BCL6 deletion in established DLBCL tumors in vivo induced a significant tumor growth inhibition with initial tumor stasis followed by slow tumor growth kinetics." (PMID 32180900, 2020). "Because terminally differentiated effector cells lose the proliferative potential, CD62L+Bcl6+ cells within the tumor must play a pivotal role in replenishing anti-tumor CD8 T cells." (PMID 32845913, 2020). "Accordingly, depleting Bcl6 in Treg cells enhanced anti-tumor capability and retarded tumor progression." (PMID 32477338, 2020). "Intriguingly, MGMT expressing tumors had a higher proportion of BCL6-positive cells than the MGMT-negative tumours." (PMID 32320427, 2020). "Knockdown of the BCL6 gene in J82 cells inhibited tumor growth and enhanced apoptosis in the NOD/SCID xenograft model." (PMID 31903146, 2020). "Tumor levels of cytokeratin-5 (CK5) correlated positively with B Cell CLL/Lymphoma 6 (BCL6) in premenopausal women with hormone positive breast cancer." (PMID 31114446, 2019). "All these results showed the 1E6A4 mAb had good potential value to detect BCL6 expressing tumor cells in clinic." (PMID 31063496, 2019). "We split patients in the training cohort in five groups, according to the tumor BCL6, CD11c, BCL2, and LAIR1 expression (high/low), and then performed Kaplan Meier analyses to determine the overall survival (OS) in the function of the expression level." (PMID 31336593, 2019).